MYD88 (MYD88 innate immune signal transduction adaptor)
Diseases named in the same sentence as MYD88 in open-access papers (continued):
Sharing a sentence is not in itself a finding about the gene and the disease.
ovarian carcinoma (continued). "Our group and others have previously demonstrated that TLR4, MyD88 and MAD2 play key roles in paclitaxel resistance in ovarian cancer and are associated with poor patient outcome." (PMID 33370338, 2020). "Recently, XIAP has been reported in the PTX-induced TLR4/MyD88-dependent signaling pathway in ovarian cancer." (PMID 29486738, 2018). "In vitro TRX-E-002-1 has potent cytotoxic activity against human cancer cells including CD44+/MyD88+ ovarian cancer stem cells." (PMID 28013349, 2017). "TRX-E-002-1 is able to induce cell death in chemo-resistant CD44+/MyD88+ OCSC clones and chemo-sensitive CD44−/MyD88− ovarian cancer cell lines when grown separately or in co-cultures which mimic tumour heterogeneity." (PMID 28013349, 2017). "The relationships between the expressions of TLR-4, MyD88, and NF-κB have been examined in epithelial ovarian cancer patients." (PMID 26881027, 2016). "Specifically curcumin and quercetin as a ligand of MD-2 or TLR4 potently repress TLR4/MyD88/NF-кB signal pathway and inhibit immunosuppressive cytokine production, and suppress ovarian cancer cell metastasis." (PMID 27118139, 2016). "Certainly, the role of TLR4/MD-2 complex for activation of MyD88/NF-κB signaling needs to be further studied in a variety of ovarian cancer cell lines of different phenotypes, and even in vivo study." (PMID 27118139, 2016). "Active TLR-4/MyD88 signalling was also found in epithelial ovarian cancer cells and influenced the drug response." (PMID 26881027, 2016). "All of the present data suggested NAG-1 protein as a crucial mediator of EOC progression and resistance to the standard first-line chemotherapy against EOC, particularly in MyD88-positive ovarian cancer stem-like cells." (PMID 27708225, 2016). "The activation of TLR4/MyD88/NF-κB signaling enhances aggressive tumor phenotype with poorer clinical outcome in epithelial ovarian cancer patients." (PMID 27655682, 2016). "Our data demonstrate that miRNA-149 is associated with the cellular response to paclitaxel through regulation of MyD88 in ovarian cancer cells." (PMID 26223974, 2015). "Overexpression of MyD88 decreases the sensitivity to paclitaxel in ovarian cancer and hepatocellular carcinoma cells." (PMID 26223974, 2015). "Taken together, our findings suggest that miR-149 facilitates the migration of ovarian cancer cells through regulation of MyD88." (PMID 26223974, 2015). "Collectively, the data indicate that miRNA-149 has the potential to regulate MyD88 expression in ovarian cancer cells." (PMID 26223974, 2015). "Ex vivo manipulation of ovarian cancer stem cell (CSC) differentiation can decrease MyD88 expression, providing a potentially valuable CSC model for ovarian cancer." (PMID 24977712, 2014). "The present study investigated the effect of TLR4 ligation by Pac in MyD88-positive (MyD88+) and MyD88-negative (MyD88−) human ovarian cancer cell lines." (PMID 24527095, 2014). "Several cell surface antigens such as CD44, CD117, CD133 and MYD88 have been used to isolate ovarian cancer stem cells." (PMID 23782518, 2013). "MyD88 positive EOC cells have a functioning TLR4/MyD88 pathway and are possibly indicative of an ovarian cancer stem cell that is highly resistant to pro-apoptotic signalling." (PMID 22533866, 2012). "We previously showed, using gene expression microarray, that Ck18 expression is 7-fold higher (P = 0.0007) in CD44+/MyD88+ EOC stem cells compared to the CD44−/MyD88− mature ovarian cancer stem cells (mOCCs)." (PMID 21904548, 2011). "The signaling cascade involving TLR4 and MyD88 is understood to promote the development and spread of breast cancer, with its suppression being recognized as a promising treatment strategy for hepatocellular carcinoma and epithelial ovarian cancer." (PMID 39390599, 2024).
ovarian carcinoma (continued). "Accordingly, we proposed that inflammation may be involved in the acquisition of chemoresistance through the MyD88 expression in ovarian cancer cells." (PMID 35464826, 2022). "In addition, MyD88-positive EOC cells have a functioning TLR4/MyD88 pathway and are possibly indicative of an ovarian cancer stem cell that is highly resistant to proapoptotic signaling." (PMID 35464826, 2022). "However, in ovarian cancer it was also revealed that Myd88 expression strongly correlated with TRL4 expression and provided a favorable prognosis." (PMID 33669782, 2021). "Similarly, in epithelial ovarian cancer, miR-146a directly regulated the sensitivity of ovarian cancer cells to drug therapy and was also shown to target and reduce MyD88 expression, thus inhibiting NF-κB activation." (PMID 32276464, 2020). "Elevated expression levels of TLR4 or it’s adaptor protein MyD88 have been associated with reduced survival outcome in HGSOC patients, while therapeutic targeting of TLR4 has been shown to restore paclitaxel sensitivity in ovarian cancer cell models." (PMID 33370338, 2020). "Furthermore these miRs target WNT signaling, AKT/mTOR signaling and TLR-4/MyD88 to regulate ovarian cancer progression and resistance." (PMID 31608277, 2019). "PTX could induce NF-κB and cJUN activation to promote IL-6, IL-8, VEGF and MCP-1 productions via a TLR4/MyD88-dependent pathway and resisted drug-induced apoptosis in ovarian cancer." (PMID 29486738, 2018). "Furthermore, miR-146a was also shown to target and reduce MyD88 expression, thus inhibiting the NF-κB activation in epithelial ovarian cancer, and directly regulating the sensitivity of ovarian cancer cells to drug therapy." (PMID 29616037, 2018). "One study was carried out using a cell population CD44+MyD88+ enriched in epithelial ovarian cancer stem cells: this cell population exhibits multiple properties of ovarian cancer stem cells, including chemoresistance and the property to differentiate into multiple cell types." (PMID 29389895, 2018). "For instance, prolonged NF-κB activation and the subsequent production of pro-inflammatory chemokines in myeloid differentiation protein 88 (MyD88)-expressing epithelial ovarian cancer cells are involved in chemoresistance to paclitaxel, a crucial drug for standard first-line chemotherapy." (PMID 27708225, 2016). "For example, the TLR2-MyD88-NF-κB signaling pathway supports a proinflammatory microenvironment together with the expansion of the CD44+/MyD88+ epithelial ovarian cancer (EOC) stem cells by enhancing self-renewal, as shown by the upregulation of stemness-associated genes." (PMID 28116318, 2016). "Type I cells are characterized by slower growth, cancer stem-like properties, and a high level of MyD88, which contributes to ovarian cancer progression by inducing epithelial ovarian cancer cell proliferation, survival, and metastasis, as well as tumor angiogenesis and paclitaxel chemoresistance." (PMID 27708225, 2016). "In this study, we investigated whether miRNA-149 modulates cellular sensitivity to paclitaxel by regulating the expression of MyD88 in ovarian cancer A2780 cells." (PMID 26223974, 2015). "Characterisation of TLR4 & MyD88 expression in ovarian cancer." (PMID 24977712, 2014). "In summary, this data provides additional support to the hypothesis that MyD88 expression is an adverse prognostic factor in ovarian cancer, for which evidence has been mounting in recent studies." (PMID 24977712, 2014). "The novel analysis of miR-21 and miR-146a expression in this study, based on the categorization of EOC into MyD88 positive and MyD88 negative, demonstrates that expression of both MyD88 and these microRNAs are linked to ovarian cancer." (PMID 24977712, 2014).
ovarian carcinoma (continued). "In EOC, we and others have shown that CD44+/MyD88+ epithelial ovarian cancer stem cells (EOC stem cells) possess tumor-initiating properties and exhibit diverse resistance to a wide-range of chemotherapy agents including, but not limited to, platinums and taxanes." (PMID 25237928, 2014). "In CD44+MyD88+ ovarian CSC/TICs from either ovarian cancer tissues or ovarian ascites, hypoxia/HIF-1 is an extracellular signal that may initiate differentiation of CSC/TICs by triggering TWIST1 expression." (PMID 23528891, 2013). "The aim of this study, therefore, was to assess whether there was any molecular link between MAD2, TLR4 and MyD88 in ovarian cancer and to further explore the mechanisms each of these biomarkers utilise, in order to render ovarian cancer cells resistant to paclitaxel therapy." (PMID 33370338, 2020). "MyD88 positive EOCs have a functioning TLR4/MyD88 pathway and may represent an ovarian cancer stem cell (CSC) that is highly resistant to pro-apoptotic signaling and which can recruit leukocytes to actively promote a pro-inflammatory, pro-proliferative microenvironment." (PMID 24977712, 2014). "We believe that it supports the hypothesis that EOC MyD88 positive cells may be stem-like due to their MyD88 expression pattern and also demonstrates a practical and easily manipulated cancer stem model with relevance to ovarian cancer." (PMID 24977712, 2014). "In addition, MyD88 staining has being optimised for cytological analysis of ascites which could have an important role to play in ovarian cancer treatment, in particular in the neoadjuvant setting." (PMID 24977712, 2014). "The significance of our findings is the possibility of developing new venues to target the surviving CD44+/MyD88+ EOC stem cells as part of maintenance therapy and therefore preventing recurrence and metastasis, which are the main causes of mortality in patients with ovarian cancer." (PMID 24403249, 2013). "LINC00886 drives ovarian cancer progression and immune escape through themiR-423-5p/TLR4/Myd88/NF-κB/PD-L1 axis, establishing its potential as both a prognostic biomarker and therapeutic target." (PMID 40999508, 2025). "In ovarian cancer, high expression of TLR4 and MyD88 was found to predict poorer overall survival in patients with EOCs." (PMID 36765715, 2023). "In order to discern a possible relationship between MAD2 and TLR4-MyD88 signalling, transfection experiments were performed initially in both A2780 (MyD88 null) and SKOV-3 (MyD88 positive) ovarian cancer cells." (PMID 33370338, 2020). "This was investigated using siRNA knockdown of MAD2, TLR4 and MyD88 in two ovarian cancer cell lines, A2780 and SKOV-3 cells and overexpression of MyD88 in A2780 cells." (PMID 33370338, 2020). "For example, the knockdown of MyD88 results in a failure of ovarian cancer cell proliferation and cytokine production in response to LPS, suggesting that TLR4-MyD88 cell signaling contributes to epithelial ovarian cancer growth." (PMID 29928275, 2018). "Purified populations of OCSCs CD44+/MyD88+ cells are able in vitro and in vivo to differentiate into CD44+/MyD88− mature epithelial ovarian cancer cells." (PMID 29389895, 2018). "The results of the present study support that MyD88 acts as a downstream factor and combines with TLR4 to increase the proliferation of ovarian cancer cells." (PMID 24527095, 2014). "It is possible that the combination of MyD88, MAD2 and other ovarian cancer bio-markers can permit patient-specific treatments to be developed." (PMID 25495823, 2014). "MyD88+ human ovarian carcinoma cells (SKOV3 and OVCAR3) and MyD88− ovarian carcinoma cell lines (A2780 and 3AO) were selected to investigate the TLR4 effects on apoptosis with Pac chemotherapy." (PMID 24527095, 2014). "The present study investigated the role of TLR4 in ovarian cancer cells and the effect of TLR4 ligand by Pac in MyD88+ and MyD88− human ovarian carcinoma in vitro." (PMID 24527095, 2014).
ovarian carcinoma (continued). "We show that in contrast to the more differentiated ovarian cancer cells, the putative CD44+/MyD88+ ovarian cancer stem cells express lower levels of pyruvate dehydrogenase, Cox–I, Cox-II, and Cox–IV, and higher levels of UCP2." (PMID 25237928, 2014). "CD44+ cells, including CD44+MyD88+ cells from either ascites or tumor tissues and CD44+CD24+EpCAM+ cells from ovarian cancer cell lines, exhibit the molecular phenotypes of ovarian CSC/TICs." (PMID 23528891, 2013). "Ovarian cancer tumors are heterogeneous and in our previous reports we have shown that both subtypes of cells (CD44+/MyD88+ and CD44−/MyD88−) are present in the tumors." (PMID 24403249, 2013). "To demonstrate the role of TLR4/MyD88 signaling in ovarian epithelial cancers (OECs), we examined the expression of TLR4, MyD88 and nuclear factor- κB (NF-κB) in OECs." (PMID 22985132, 2012). "While resistance to T. gondii depends on MyD88‐mediated IL‐12 production, it is not crucial for the anti‐tumor responses of ovarian cancer." (PMID 38109851, 2024). "Moreover, the IL-6 cytokine secreted by adipocytes plays a crucial role in the inhibition of mitochondria-triggered apoptosis in chemoresistant ovarian cancer stem cells (CSCs), particularly in the CD44+/MyD88+ cancer cell population." (PMID 38201468, 2023). "All eight MYD88 splice isoforms were also detectable in non-immune cells, as verified in a publicly available RNAseq dataset for ovarian cancer." (PMID 34163463, 2021). "A number of markers expressed on ovarian cancer stem cells have been described in the literature: CD133 (prominin), ALDH (aldehyde dehydrogenase), CD44 (hyaluronan), CD117 (c-kit), MyD88 (myeloid differentiation primary response protein), CD24 (mucin-like adhesion molecule)." (PMID 34440558, 2021). "In human epithelial ovarian cancer tested on tissue samples of 500 patients by immunohistochemistry, it was shown that expression of TLR4 and MyD88 predicts poorer overall patient survival apparently due to favoring inflammatory microenvironment at the site of tumor growth." (PMID 30976817, 2019). "Our earlier report also demonstrates that in absence of TLR4/MyD88 signalling, ovarian cancer chemoresistance is maintained by NF-κB transcriptional activation under cisplatin treatment." (PMID 29169370, 2017). "In ovarian cancer, CD44+/MYD88+expression denotes stem-like property and chemoresistance." (PMID 27655682, 2016). "We used two subtypes of ovarian cancer cells based on their expression of CD44 and MyD88." (PMID 24403249, 2013). "Indeed, like that of ID8 ovarian cancer, the therapeutic efficacy of cps therapy was not dependent on the MYD88 signaling pathway." (PMID 38109851, 2024). "Moreover, TRX-E-002-1 was effective against chemoresistant cancer stem cell (CD44+ MyD88+) populations in both 2D and 3D models as well as having potent cytotoxic activity against non-stem like ovarian cancer cells." (PMID 29572477, 2018). "However, the activated EGFR was not involved in NF-κB activation in MyD88-positive ovarian cancer cells." (PMID 27708225, 2016). "In breast, prostate, and ovarian cancers, studies using their corresponding cancer cell lines or primary cancer cells from patients all provided evidence to support that LPS could promote production of proinflammatory cytokines from cancer cells by signaling through TLR4 and MyD88." (PMID 36765715, 2023). "Moreover, ovarian cancer chemokines such as IL-8 and CXCL-1 and stemness marker OCT4 were suppressed by NAG-1 in SKOV3 cells, indicating that NAG-1 expression positively regulates not only pro-inflammatory signals but also cancer stemness biomarkers in MyD88-positive type I EOC cells." (PMID 27708225, 2016). "Although the production of MyD88-dependent IL-12 is essential to resist T. gondii infection, MyD88 is not necessary for the anti-tumor response of B16F10 melanoma and ovarian cancer, but is required for pancreatic cancer." (PMID 36118042, 2022).
ovarian carcinoma (continued). "According to CD44 positivity these authors distinguished two types of tumor cells: type I ovarian cancer cells, CD44+ALDH1+, MyD88+, large and non-dividing; type II ovarian cancer cells, CD44−, ALDH1−, MyD88−, small and rapidly dividing." (PMID 29389895, 2018).